CXCL9 (C-X-C motif chemokine ligand 9)
Diseases named in the same sentence as CXCL9 in open-access papers (continued):
Sharing a sentence is not in itself a finding about the gene and the disease.
tumor (continued). "Gene expression analysis revealed that BCG injection elicits the expression of a vast array of chemokines in tumor lesions, including strong expression of CXCL9, 10, and 11, a set of chemokines that attract T cells expressing the CXCR3 chemokine receptor." (PMID 28424760, 2017). "All together, these data indicate that the presence of galectin-3 is a limiting factor for IFNγ-induced CXCL9/10 expression by tumor cells." (PMID 28986561, 2017). "Galectin antagonists increased strongly CXCL9 expression in tumor xenografts and human biopsies, supporting the notion that galectin-3 lattices in the tumor ECM are the important players of IFNγ retention." (PMID 28986561, 2017). "This is likely mediated through a CXCR3-dependent chemoattraction of tumor cells to the enhanced secretion of the chemokine ligands, CXCL9 and 10, by peritoneal membrane fibroblasts (PMF)." (PMID 29050279, 2017). "T-cell recruitment towards the tumor requires a chemokine gradient of the critical IFNγ-induced chemokines CXCL9/10/11." (PMID 28986561, 2017). "We conclude that inhibition of galectins releases the IFNγ trapped in the matrix of human tumor biopsies, facilitating IFNγ diffusion, and consequently increasing CXCL9 expression." (PMID 28986561, 2017). "CXCL9 and −10 have also been reported to attract tumor-infiltrating lymphocytes and immunological infiltrates, positively linked with better clinical outcomes in human serous ovarian cancer." (PMID 28359286, 2017). "Further contributing to the tumor suppressing function of Th17 cells is the production of the chemokines CXCL9 and CXCL10, which facilitates the recruitment of CD8+ T cells into the tumor." (PMID 28938918, 2017). "Th1-derived IFN-γ is known to cause macrophage cytotoxicity to tumour cells and to stimulate macrophages to produce the angiostatic factors CXCL10/IP-10 and CXCL9/MIG." (PMID 29089667, 2017). "The anti-tumor M1 TAMs produce IL-12, IL-6 and CXCL9 to stimulate the immune system, and express iNOS to kill tumor cells directly through production of nitric oxide." (PMID 29037250, 2017). "By contrast, CXCR3-B is anti-angiogenic in this context, interacting with CXCL-9 to depress endothelial cell proliferation and tumour angiogenesis." (PMID 29157300, 2017). "By adding galectin antagonists to the IFNγ-supplemented medium, we expected to improve the diffusion of IFNγ in a tumor microenvironment supposedly enriched in galectins, thereby increasing CXCL9 expression." (PMID 28986561, 2017). "In mouse models, the CXCL9 produced by tumor cells in response to IFNγ was found responsible for T-cell infiltration." (PMID 28986561, 2017). "Trapping IFNγ in the ECM would reduce the CXCL9/10 gradient, thereby limiting T-cell infiltration in the tumor." (PMID 28986561, 2017). "The results suggest that high expression of CXCL9 will be induced by direct contact of the endothelial cells and tumor cells." (PMID 27738495, 2016). "Serum CXCL9 levels were correlated with pT status, pathological overall stages, tumor depths, and positive bone invasion." (PMID 27726306, 2016). "An increasing body of evidences has been demonstrated that CXCL9 acts as a tumor promoter in multiple types of cancer." (PMID 27726306, 2016). "This review for the first time presents the most comprehensive summary for the role of CXCL9 in different types of tumors, and demonstrates its contradictory role of CXCL9 in tumor progression." (PMID 27726306, 2016). "Previously, we demonstrated that pro-inflammatory chemokines CXCL9 and CXCL10 were associated with an increase in tumor infiltrating CD8+ T cells." (PMID 27369431, 2016). "CXCL9 will draw more researchers’ interests and attention in the future because of its contradictory and key effects on tumor initiation and development." (PMID 27726306, 2016). "To analyze the mechanism by which MSCs-Sirt1 recruit NK cells for tumor inhibition, we measured the serum levels of chemokines CXCL9, CXCL10, and CXCL11." (PMID 27764779, 2016).
tumor (continued). "CXCR3, a G-protein coupled receptor of chemokine CXCL9, is significant in tumor progression and angiogenesis, and also has been found to be correlated with poor prognosis for breast tumors, melanoma, and colon and renal cancer patients." (PMID 26883105, 2016). "In contrast, CCL5 and CXCL9 showed significantly higher mRNA expression levels and had increased protein levels in the SG-/- tumour tissue." (PMID 27223472, 2016). "In paired comparisons of tumour vs normal mucosa IR gene expression (n = 144), there was a trend for higher expression of CXCL9 (Wilcoxon test, p = 0.05) and lower expression of CD3Z, CXCL13 and IGHM in the malignant tissue." (PMID 25970543, 2015). "HPV-positive tumor tissue-derived cell cultures produced much higher levels of chemokines, namely CXCL9, CXCL10, CXCL12, CCL17 and CCL21." (PMID 25949860, 2015). "HPV-positive tumor tissue-derived cell cultures produced markedly higher levels of chemokines, namely CXCL9, CXCL10, CXCL12, CCL17 and CCL21, and slightly higher levels of the cytokines IL-2, IL-17, IL-23 and IFNγ." (PMID 25949860, 2015). "Mouse (host) microarray analysis showed a significant increase in the NK cell damage response receptor CXCR3, which binds tumor-cell specific membrane-bound activation ligands CXCL9, CXCL10, and CXCL11, all of which were also increased on the human array." (PMID 25952672, 2015). "Next, we measured mRNA levels for IFN-γ, FasL, CCL2, and CXCL9 in the lung from tumor-bearing WT and iNOS-KO mice after GalCer administration." (PMID 26496031, 2015). "In contrast, trafficking of antigen-activated CXCR3-expressing NK, CTL, and/or Th1 cells into tumor tissue is promoted via the action of CXCL9 and CXCL10, two IFNγ-inducible chemokines." (PMID 23408142, 2013). "Statistical analysis of the 40 paired samples available from these 86 patients demonstrated that CXCL9 expression (score) was significantly higher in tumor cells versus normal epithelial cells (135.7±70.1 vs. 65.2±63.2, P<0.0001)." (PMID 24278236, 2013). "The ability of CXCL9 protein (migratory monokine-induced by interferon-γ) to modulate host cell infiltration and tumor behavior is known; CXCL9 protein expression also results in smaller tumors and decreased rate of tumor metastasis." (PMID 23405235, 2013). "Serum CXCL9 levels were significantly higher in NPC patients with higher tumor stages, nodal stages, and overall stages (P<0.001, P = 0.001, and P<0.001, respectively)." (PMID 24278236, 2013). "CXCL9 positive cells were found to be scattered throughout the tumor mass with the various degree of intratumor heterogeneity." (PMID 24278236, 2013). "To distinguish which cell types in the tumor mass expressed CXCL9, we performed immunohistochemical staining of tissue sections from 86 patients with NPC." (PMID 24278236, 2013). "Such recruitment to tumor sites occurs via CXCR3 mediated chemotaxis in response to the CXCL9-11 chemokines, produced within the TME." (PMID 23326300, 2013). "Pretreatment CXCL9 serum concentrations were significantly higher in patients with higher tumor stages, nodal stages, and overall stages (P<0.001, P = 0.001, and P<0.001, respectively)." (PMID 24278236, 2013). "Transcripts for CXCL9 (fold-change) were significantly elevated in NPC tumor specimens as compared with adjacent normal tissue (8.2±10.3 vs. 4.3±6.5, P = 0.016)." (PMID 24278236, 2013). "CXCL9 is produced in the tumor-microenvironment in response to IFNγ production, and can attract CXCR3+ T cells into the tumor." (PMID 22359647, 2012). "Our results show that endothelial and/or stromal cells within the tumour express higher levels of mouse-specific cytokines (MCSF, IFNG, IL5, IL7 and CXCL9) in VEGFA165 tumours compared with control tumours." (PMID 22045186, 2011). "Tumour endothelial cells demonstrated a more than 11-fold increase in CXCL9 mRNA expression and a 3- to 20-fold increase in CXCL10 mRNA expression, as compared with BECs or LECs in all samples." (PMID 21179030, 2011).
tumor (continued). "As such, we observed that CXCL9 is highly expressed in TuECs, especially in their luminal (apical) side of the tumour vessel." (PMID 21179030, 2011). "There was a significant increase in expression levels of CXCL9, which correlates with an anti-tumor environment." (PMID 21884585, 2011). "In addition, two key chemokines, CXCL9 and CCR3, which are known to promote CD8+ T cell recruitment into the tumor microenvironment (TME), were upregulated in the high-risk group." (PMID 41584042, 2026). "Functionally, VISTA deficiency is linked to a shift in tumor-associated macrophages (TAMs) from an immunosuppressive phenotype marked by secreted phosphoprotein 1 (SPP1), to one enriched for C-X-C motif chemokine ligand 9 (CXCL9), indicative of a pro-inflammatory state." (PMID 41776161, 2026). "Which signals induce this cellular state in tumours remains unclear, but CXCL9 expression by cDC1s can be augmented therapeutically by increasing uptake of tumour‐derived DNA in response to TIM‐3 blockade." (PMID 40745918, 2025). "In addition, LIF impairs anti‐PD1 therapy by modulating CXCL9 expression in tumor‐associated macrophages (TAM), ultimately disrupting the infiltration of CD8+ T cells into the tumor microenvironment." (PMID 40416597, 2025). "Therefore, selectively activating the CXCL9/10/11-CXCR3 paracrine axis is suggested to be a more effective anti-tumor strategy." (PMID 40867314, 2025). "Moreover, intrigued by the significantly increased expression of the CXCL9 cytokine in recurrent tumour ROIs compared to primary, we wished to examine the expression levels of other cytokines." (PMID 41168392, 2025). "Furthermore, eosinophils promote TAM polarization toward anti-tumor M1-like phenotypes via CXCL9 secretion, which recruits CD8 + T cells to bolster immune checkpoint inhibitor (ICI) efficacy." (PMID 40380196, 2025). "RT has been found to upregulate the expression of specific chemokines, including C–C motif chemokine ligand 5 (CCL5) and C–X–C motif chemokine ligand 9 (CXCL9), which play crucial roles in recruiting and guiding T cells to the tumor site, further improving T‐cell‐mediated tumor control." (PMID 40416596, 2025). "For example, decreased CXCL9 suggested that a reduction in CD8+ CHRNA7KO tumor-infiltrating CD8+ lymphocytes (TILs) may be a recruitment defect, while increased CCL2 could be related to the recruitment of myeloid-derived suppressor cells." (PMID 40653990, 2025). "Additionally, given the strict interactions with T cells in the TME, eosinophils represent promising candidates to support CAR T cells facilitating their entry into the tumor through release of T cell-attracting chemokines (i.e., CXCL9, CXCL10)." (PMID 40050933, 2025). "Astaxanthin was associated with a higher quantity of tumor‐associated macrophages, infiltration of CD8+ T cells, Tumor Granzyme B, IL‐2, serum TNF‐α and interferon‐γ, genetic transcription of CXCL9, CXCL10, and CXCR3, and mRNA expression of cluster of differentiation." (PMID 40071130, 2025). "Two distinct cDC1 activation states are differentially associated with Cxcl9 and Il12b/Ccr7 expression, respectively, each localising to different regions of the tumour, with the Cxcl9+ cDC1s being enriched in the parenchyma while the Il12b+ cDC1s remain located at the edges." (PMID 40745918, 2025). "While we did not observe an increase in expression of specific CXCL9+ cell markers, which was previously reported after anti-PD-L1-CRT, we did observe double-positive macrophages/DCs, a characteristic feature of CXCL9+ cells localized around the tumour after anti-PD-L1-CRT." (PMID 40670667, 2025). "Notably, it has been reported that the expression of these chemokines, specifically CXCL9 and CXCL10, is upregulated in the tumor microenvironment of METTL3-deficient tumors." (PMID 39497707, 2025).
tumor (continued). "Lastly, analysis of a published spatial transcriptomic dataset of human tumours revealed that CCR7+ cDC1s, the human equivalent of the murine Il12b+ cDC1s, are also preferentially associated with TCF1+ T cells as compared with the CXCL9+ cDC1s." (PMID 40745918, 2025). "Furthermore, activated CXCR3+ Tregs were found in various tumours and shown to co‐localise with CXCL9+‐cDC1s in the TME of mouse transplantable tumours." (PMID 40878038, 2025). "This suggests that CXCL9 + macrophages could be a potential therapeutic target for activating anti-tumor immunity." (PMID 41325308, 2025). "The extent of overlap between CXCL9/CXCL10‐expressing and CCR7‐expressing tumour‐associated cDC1s, whether they represent end‐states or steps along the activation process and whether they have different functions, remains unclear." (PMID 40745918, 2025). "As such, CXCL9+ cDC1s may be key to recruiting effector TCF1− CD8+ T cells into the tumour parenchyma." (PMID 40745918, 2025). "Given the critical role of CXCL9 as a T-cell attractant, effective anti-tumor response of CXCL9+CD68+ cells may necessitate their proximity to T cells." (PMID 39965007, 2025). "It is important to note, however, that the anti-tumor effects of CXCL9 + macrophages likely extend beyond direct interactions with tumor cells and may also involve indirect modulation of other immune cells, such as T cells, NK cells, and B cells." (PMID 41325308, 2025). "Similarly, fungal dysbiosis in GC, including enrichment of Apiotrichum and Cutaneotrichosporon, drives inflammation through cytokines such as TNF-α and CXCL9, which suppress tumor-suppressive miRNAs and promote oncogenic pathways." (PMID 39973938, 2025). "Downregulation of CXCL9/10 – T cell signaling drives increased tumor burden in old." (PMID 41332581, 2025). "On the other hand, some studies suggest that CXCL9/CXCR3 may contribute to tumor progression and metastasis." (PMID 40145607, 2025). "Furthermore, METTL14 knockdown has been associated with increased tumor immunogenicity, as evidenced by enhanced CD8+ T‐cell infiltration and elevated secretion of IFN‐γ and CXCL9/10 within the tumor microenvironment." (PMID 41316520, 2025). "A striking feature of L-TTF2 tumors was CXCR3+CD8+-T-cell infiltration, associated with the CXCR3 ligands CXCL9/10/11/13, and tumor cell apoptosis (non-significant trend)." (PMID 40696453, 2025). "Also, M1 macrophages can recruit Th1 cells to the tumor site through the secretion of the chemokines CXCL9/10." (PMID 40303994, 2025). "Similarly, colony formation assays demonstrated that conditioned medium from M1 macrophages inhibited tumor cell colony formation, and this inhibitory effect was diminished when CXCL9 was knocked down in M1 macrophages." (PMID 41325308, 2025). "Previous studies established that the epigenetic modifier EZH2, which mediates H3K27 trimethylation and heterochromatin formation, can specifically repress the expression of Cxcl9 and Cxcl10 in several tumor entities, leading to the exclusion of cytotoxic T cells and NK cells from the TME29,30." (PMID 40562773, 2025). "Notably, a subset of luminal cells clustering adjacent to tumor cells by UMAP showed enrichment of Cxcl9 expressing cells." (PMID 41332581, 2025). "Notably, two interferon-stimulated genes (ISGs) belonging to the CXCL chemokine family, Cxcl9 and Cxcl10, were the two most downregulated genes in the old tumor compartment." (PMID 41332581, 2025). "Additionally, IL-7 supports T cell survival and homeostasis, while CXCL9 plays a role in effector T cell recruitment to the tumor." (PMID 40630200, 2025). "In sum, various studies have reported a role for IL‐12 and CXCL9 in anti‐tumour immunity." (PMID 40745918, 2025). "We conclude that Cxcl9/10 are specifically downregulated in aged mouse HER2+ tumor cells." (PMID 41332581, 2025). "Moreover, we found that CXCL9 was expressed not only by macrophages/DCs but also by some tumour cells and lymphocytes." (PMID 40670667, 2025).
tumor (continued). "Type-II interferon (IFN-γ) inflammatory signaling induces PD-L1 expression on cancer cells, conducive for tumor immune evasion, and at the same time upregulates chemokines such as CXCL9/CXCL10 that recruit CXCR3+ effector T cells as a cytotoxic response to cancer." (PMID 41440526, 2025). "The high PRMTScore group may promote tumor cells to secreta chemokines (such as CXCL9/10), recruit immune cells such as CD8+ T cells, and induce immune escape of PD-L1 expression." (PMID 40399547, 2025). "Additionally, we found that stem‐like TCF1+ CD8+ T cells are enriched in tumour‐bordering regions in association with the Il12b/Ccr7‐expressing cDC1s, while effector CD8+ T cells were enriched in the parenchyma in proximity to Cxcl9+ cDC1s." (PMID 40745918, 2025). "Chemokines are key mediators of T-cell migration, but tumours frequently downregulate the expression of chemokines required for T-cell homing, such as CXCL9 and CXCL10, while upregulating signals that preferentially attract immunosuppressive cells, such as Tregs and MDSCs." (PMID 40624498, 2025). "Moreover, it highlighted the importance of the presence of CXCL9+CD68+ throughout tumor regions and their proximity to CD8+ T cells." (PMID 39965007, 2025). "These genes included key immune modulators, such as Cxcl9 and Cxcl10, responsible for recruiting CD8+ T cells, and H2-K1 and H2-D1, encoding MHC class I (MHC-I) genes crucial for antigen presentation and thus tumor recognition by CD8+ T cells." (PMID 39540840, 2025). "Cxcl9 is considered a positive prognostic marker along with Pten which is a tumor suppressor." (PMID 40568084, 2025). "CXCL9 and CXCL10 were associated with increased tumor infiltrating CD8+T cells." (PMID 40242222, 2025). "In another study, ginseng-derived EVs reprogram tumor-associated macrophages (TAMs), increasing the secretion of CCL5 and CXCL9 to recruit CD8+ T cells into the tumor core, thereby enhancing the efficacy of immune checkpoint blockade therapy with PD-1 monoclonal antibodies." (PMID 40630801, 2025). "Hence, co-localisation of monocytes/macrophages and CD4+ T cells coincided with CXCL9/CXCL10 expression in human tumours." (PMID 40523200, 2025). "mRNA expression of CXCL9, iNOS, and IL-12β, anti-tumor macrophage markers, was elevated, while mRNA expression of IFNγ, TNFα, ARG-1, TGFβ, IL-10, and VEGFa, pro-tumor macrophage markers, was significantly lower in TAMs isolated from the prostates of RON∆Epi/TRAMP+ compared to RONF/F/TRAMP+ mice." (PMID 40282397, 2025). "Interestingly, when we analysed the tumour cDC2 compartment by flow cytometry, CXCL9+ cDC2s were also detected while IL‐12p40+ cDC2s were very rare." (PMID 40745918, 2025). "Conversely, to test whether enhancing Cxcl9/10 expression could suppress tumor growth in old mice, we co-expressed mouse Cxcl9/10 with the same Her2/neu used in this study using a lentivirus P2A expression system." (PMID 41332581, 2025). "By combining the high-resolution advantages of single-cell RNA sequencing for cell subpopulation analysis with the rich patient prognosis information from bulk RNA sequencing, we explored the potential anti-tumor capabilities of CXCL9 + macrophages and discussed their possible mechanisms." (PMID 41325308, 2025). "Additionally, upregulation of antigen presentation genes including H2-Aa, H2-Ab1, H2-Eb1, Tapbp and Cd74 as well as Stat1 and Cxcl9 - a chemokine that recruits immune cells to the tumor, was observed in the CAR-T group." (PMID 40568084, 2025). "Additionally, IκBζ suppresses Cxcl9, Cxcl10, and Ccl5 expression via HDAC3 and EZH2, which impairs the recruitment of NK and CD8+ T cells into the tumor, causing resistance to α-PD-1 immunotherapy in mice." (PMID 40562773, 2025). "This macrophage population is reprogrammed by the IFN-I signaling transmitted from tumor cells, leading to increased expression of T cell chemokine CXCL9/XCL10 and upregulation of the antigen-presenting machinery, thereby boosting CD8+ T cell–mediated antitumor immunity." (PMID 41321309, 2025).